ERO1A (endoplasmic reticulum oxidoreductase 1 alpha)
Diseases named in the same sentence as ERO1A in open-access papers (continued):
Sharing a sentence is not in itself a finding about the gene and the disease.
cancer (continued). "By maintaining redox balance and supporting mitochondrial function, ERO1α helps cancer cells survive and grow, especially in tumors with high mTORC1 activity." (PMID 41226317, 2025). "Wang (2024) investigated how ERO1α affects ferroptosis resistance, particularly in mTORC1-activated cancer cells." (PMID 41226317, 2025). "ERO1A is upregulated in many types of cancer, and its upregulation correlates with a worse clinical outcome." (PMID 39962052, 2025). "An important functional role of ERO1α in cancer biology lies in its role in promoting angiogenesis, primarily through the post-transcriptional regulation of VEGF-A." (PMID 41226317, 2025). "We identified IL-6 as a novel target of ERO1α and confirmed the suggestion by previous studies conducted using other cancer cell models that STAT3 directly transcriptional regulates SLC7A11." (PMID 38610018, 2024). "This suggests combining ERO1α inhibition with ferroptosis inducers in the treatment of mTORC1-related cancer to achieve better outcomes." (PMID 38610018, 2024). "Because mTORC1 regulates the ERO1α/SLC7A11 signaling network in multiple human cancer cell lines in vitro, we predicted that this signaling regulation should also exist in human tumors in vivo." (PMID 38610018, 2024). "Further study is warranted to test the safety and efficacy of anti-ERO1A therapy in various cancers." (PMID 37769655, 2023). "Hereby, ERO1α plays a pivotal role in cancer progression and potentially immune escape; making ERO1α an emerging attractive putative target for the treatment of cancer." (PMID 33615311, 2020). "In order to verify the hypoxia difference between PNI-positive and PNI-negative tumors, we detected the protein expression of ERO1A, a novel endogenous marker of hypoxia in cancer, in 49 GC tissues of the AHJU cohort." (PMID 32373527, 2020). "Accordingly, when WT or ERO1α-KO cancer cells were injected into BALB/c nu/nu mice, the enzyme-deficient tumors failed to develop whereas wild-type cells were highly tumorigenic in vivo." (PMID 31666928, 2019). "Additional studies, including the analysis of various carcinomas in vitro and samples from patients, are necessary to establish the prognostic value of ERO1α." (PMID 31142270, 2019). "ERO1α is overexpressed and is a poor prognosis factor in various kinds of cancers including breast, colon, and pancreatic cancer." (PMID 30377291, 2018). "Mounting evidence demonstrates that expression of ERO1α, an endoplasmic reticulum (ER)-resident oxidase, is a poor prognosis factor in a variety of human cancers." (PMID 30377291, 2018). "Another report showed that ERO1α promotes cancer progression through modulation of integrin-β1 modification in colorectal cancer." (PMID 30377291, 2018). "We previously showed that ERO1α is overexpressed in various types of cancer and we further identified ERO1α expression as a novel factor related to poor prognosis in cancer." (PMID 28839225, 2017). "Collectively, these findings suggest that ERO1α regulates cancer progression by activating integrin signalling under hypoxia." (PMID 28839225, 2017). "Studies have found that ERO1α is more correlated with cancer than ERO1β." (PMID 41333024, 2025). "Interestingly, the extent of hypoxia-induced ERO1α expression appears to vary across different cancer cell lines." (PMID 41226317, 2025). "More research is needed to better understand this process and explore whether targeting ERO1α could be a useful strategy for cancer treatment." (PMID 41226317, 2025). "Recently ERO1α has gained increased attention for its role in cancer progression." (PMID 41226317, 2025). "Furthermore, by maintaining ER homeostasis, ERO1α allows cancer cells to continue secreting pro-tumorigenic factors and avoid activation of the UPR." (PMID 41226317, 2025). "Previously, we reported that ERO1A is upregulated in different cancer types." (PMID 39962052, 2025).
cancer (continued). "In addition, studies using genetic strategies to reduce or ablate the expression of ERO1A in cancer cell line models have demonstrated that a reduction in ERO1A levels inhibits growth and metastasis in vivo." (PMID 39496753, 2024). "Therefore, ERO1α inhibition combined with ferroptosis induction constitutes a new and effective therapeutic strategy for some mTORC1-related cancers." (PMID 38610018, 2024). "Therefore, the regulatory pathway of SLC7A11 by the ERO1α/IL-6/STAT3 axis presents in human cancer cells with hyperactivated mTORC1 signaling." (PMID 38610018, 2024). "Multiple lines of evidence propose ERO1α as an attractive potential target for cancer treatment." (PMID 38454454, 2024). "ERO1A has recently emerged as an interesting putative target for the treatment of cancer." (PMID 39496753, 2024). "However, more specific and potent inhibitors are warranted to fully pharmacologically validate ERO1A as a target for the treatment of cancer, which is a current focus of our laboratory." (PMID 39496753, 2024). "Together, these data indicate that ERO1A may be an important regulator of secretion of matrix in cancer cells." (PMID 39496753, 2024). "Experimental data continues to support ERO1A as an attractive target for the treatment for cancer." (PMID 39496753, 2024). "ERO1A expression was also found to correlate with multiple immune checkpoints in pan-cancers." (PMID 37769655, 2023). "Our study highlights the potential of ERO1A as a therapeutic target in cancer immunotherapy." (PMID 37769655, 2023). "Recently, accumulating data uncovers that ERO1A functions as an oncogene in many types of cancers." (PMID 38106991, 2023). "ERO1-α controls oxidative folding and ER redox homeostasis, and regulates ER Ca2+ flux and subsequent mitochondrial Ca2+ accumulation, which has been reported to be highly expressed in several types of cancer." (PMID 33634130, 2021). "This review will discuss the potential of ERO1α as target for the treatment of cancer." (PMID 33615311, 2020). "In conclusion ERO1α is emerging as an attractive target for the treatment of cancer." (PMID 33615311, 2020). "Moreover, genetic and pharmacological studies in cell lines has indicated that ERO1α expression and function contributes to an aggressive cancer phenotype." (PMID 33615311, 2020). "ERO1α can serve as a novel endogenous chronic hypoxia marker that is more reliable than CA9 and can be used as a diagnostic biomarker and therapeutic target for cancer." (PMID 31142270, 2019). "We investigated whether ERO1α, a protein that contributes to the oxidative folding of molecules involved in cancer progression, can be considered a novel, endogenous hypoxia marker." (PMID 31142270, 2019). "Our results show that ERO1α was hypoxia-induced in all the tested cancer cell lines." (PMID 31142270, 2019). "Additionally, under normoxia, ERO1α was expressed in all cell lines, though with some variations, and was relatively more abundant in the cancer cell lines than in the normal cell lines." (PMID 31142270, 2019). "Therefore, in this study, we extensively investigated the expression of ERO1α and found that it is ubiquitously expressed in cancer cells, albeit at relatively modest levels, and is considerably induced under hypoxia." (PMID 31142270, 2019). "Further studies might highlight the role of ERO1α in the prediction of cancer prognosis and the effect of ERO1α-targeting for anti-cancer therapies." (PMID 31142270, 2019). "Interestingly, some studies indicate the correlation between the severity of cancer and ERO1α positivity." (PMID 31142270, 2019). "In this study, we focused on ERO1α, a protein that is overexpressed in cancer cells." (PMID 28839225, 2017). "Here, we investigated the effect of ERO1α gene deletion on cancer biology in vitro and in vivo." (PMID 28839225, 2017).
cancer (continued). "The lack of studies that evaluate and systematically analyze the available ERO1α results have partly contributed to the ambiguity around ERO1α, and whether it could be used as a reliable marker to predict the outcome of a cancer diagnosis or an effective target for treatment." (PMID 41226317, 2025). "By consolidating molecular insights and translational considerations, this review underscores ERO1α as both a promising therapeutic target and potential prognostic marker, offering guidance for future drug development and targeted interventions in redox-dependent cancer pathways." (PMID 41226317, 2025). "Therefore, ERO1α is a potential therapeutic target for mTORC1-related cancers." (PMID 38610018, 2024). "Based on the function of ERO1A in mediating oxidative folding of proteins within the ER, we asked whether ERO1A protein expression correlates with proteins of interest that could modulate the cancer stem-like phenotype." (PMID 39496753, 2024). "In contrast, ERO1α was constitutively expressed at the mRNA and protein levels in all the cell lines investigated in this study and its expression increased under hypoxic conditions, indicating that it can be used as a hypoxic marker in a wide range of cancer cell types." (PMID 31142270, 2019). "Thus, EMT is important in cancer cell invasion and metastasis, we therefore tested to determine whether ERO1α was involved in regulation of the EMT process of cancer cells." (PMID 30377291, 2018). "Thus, ERO1α overexpression is considered to play a key role in cancer biology, and given that its expression level is positively correlated with cancer exacerbation, ERO1α could serve as a suitable target in cancer therapy." (PMID 28839225, 2017). "However, the mechanistic underpinnings of ERO1α function in cancer biology remain unclear and warrant detailed analysis." (PMID 28839225, 2017). "This difference in the selective need for ERO1A activity between healthy and TNBC makes ERO1A an ideal target for pharmacological inhibition in this cancer type." (PMID 39962052, 2025). "Broadly across cancer types, hypoxia induces ERO1α expression through the activation of HIFs, particularly HIF-1α, which transcriptionally upregulates ERO1α." (PMID 41226317, 2025). "Cancer cells adapt to harsh environmental conditions by inducing the Unfolded Protein Response (UPR), of which ERO1A is a mediator." (PMID 39962052, 2025). "Multiple studies have demonstrated that decreased ERO1α expression impairs angiogenesis by decreasing VEGF-A secretion, suggesting that ERO1αcan play a role in the angiogenesis process critical for cancer progression and metastasis." (PMID 41226317, 2025). "In this study, which primarily focused on mTORC1-activated MEFs and cancer cell lines, LSCC tissues, organoids, and PDX models, we identified ERO1α as a functional downstream target of mTORC1." (PMID 38610018, 2024). "Equally, altered protein levels of FLNA, HSPA7, HGF, ERO1A, and GARS1, have been related to cancer migration, adhesion, poor patient prognosis, and metastasis." (PMID 35008958, 2022). "ERO1L/ERO1A is involved in the production of hydrogen peroxidase (H2O2) and is a poor‐prognostic factor in cancer." (PMID 33751828, 2021). "Given the importance of ER homeostasis, ERO1α-PDI interaction, and formation of de novo disulfide bridges ERO1α has emerged as a player in the regulation and tolerance of cancer cells to ER stress." (PMID 33615311, 2020). "First, we confirmed the mRNA and protein expression of ERO1α and CA9 in various normal and cancer cell lines under normoxic in vitro culture by qPCR and WB analyses." (PMID 31142270, 2019). "ERO1α and CA9 mRNA levels in hypoxic cultures were investigated by qPCR in various cancer cell lines." (PMID 31142270, 2019). "Using quantitative real-time polymerase chain reaction, we analysed the mRNA expression of ERO1α and CA9 in different normal and cancer cell lines." (PMID 31142270, 2019).
cancer (continued). "However, the biological functions of ERO1α in cancer remain unclear." (PMID 28839225, 2017). "It further shows the therapeutic potential of interrupting the ERO1α-PDI axis, which could lead to protein misfolding; enhanced generation of reactive oxygen species (ROS); and, eventually, cancer cell death." (PMID 41751162, 2026). "Our previous studies indicated that ERO1A genetic deletion in TNBC murine models impaired VEGF folding under hypoxic conditions, affecting cancer fitness in terms of angiogenesis and dissemination, and potentiated the otherwise scant effects of antiangiogenic therapy solely targeting VEGFA." (PMID 39962052, 2025). "Likewise, ERO1A improves VEGF folding under hypoxic conditions, favoring cancer-related angiogenesis and metastasis in TNBC." (PMID 39962052, 2025). "Due to the function of protein folding in the ER, it is not surprising that genetic knockdown of ERO1A in cancer cells results in a myriad of effects on signaling." (PMID 39496753, 2024). "ERO1-α mediated ER-mitochondria Ca2+ flux activates the procaspase activating compound-1 (PAC-1) to induce ER stress and mitochondrial permeabilization, thereby promoting apoptosis in a variety of cancer cell types." (PMID 33634130, 2021). "It has been proven that Ero1-α-mediated functions are key events in the cell death induced by the procaspase-activating compound-1 (PAC-1), which promotes apoptosis in a variety of cancer cell types." (PMID 33842465, 2021). "ERO1α and PDI could be good targets in cancer indications if specificity could be achieved toward both enzymes, as PDI inhibitors tend to hit all PDI family members and ERO1α inhibitors have the tendency to target other flavoenzymes." (PMID 33615311, 2020). "ERO1α knockout (KO) by using CRISPR/Cas9 resulted in decreased tumourigenicity in vivo and reduced cell proliferation only under hypoxia in vitro, which suggested that ERO1α promotes cancer progression specifically in a low-oxygen environment." (PMID 28839225, 2017). "The absence of an ER localization signal suggests that ERO1α functions may extend beyond the ER and these additional functions based on localization of the enzyme need to be discovered in order to fully understand role of ERO1α in the progression of cancer." (PMID 33615311, 2020). "In addition, depletion of ERO1A did not alter activation of MAPK or AKT In some contexts, depletion of ERO1A levels leads to ER stress in cancer cell lines in vitro and in vivo." (PMID 39496753, 2024). "Furthermore, in the absence of ERO1α, we observed that PDA cells also displayed substantially reduced expression of the immune inhibitory molecule PD-L1, which is typically upregulated in many different cancer types." (PMID 31666928, 2019).
infection (3 papers, 2021 to 2023). The state of being infected such as from the introduction of a foreign agent such as serum, vaccine, antigenic substance or organism. "Here, we demonstrate that infection with the PEDV strain YJH/2015 triggered UPR in Vero E6 cells by activating the PERK/eIF2α pathway and led to significant increase in the expression of proapoptotic protein C/EBP homologous protein (CHOP) and ER oxidoreductase 1 alpha (ERO1α)." (PMID 36737830, 2023).
metabolic disorders (3 papers, 2021 to 2025). "The loss of SUMOylation at lysine 76 of endoplasmic reticulum protein 44 (ERP44) enhances its degradation and disrupts binding to endoplasmic reticulum oxidoreductase 1 alpha (ERO1A), protecting mice from HFD-induced metabolic disorders." (PMID 40729009, 2025).
neurodegenerative disease (3 papers, 2025). A disorder of the central nervous system characterized by gradual and progressive loss of neural tissue and neurologic function. "Therefore, ERO1α is closely related to neurodegenerative diseases, but the specific regulatory mechanism of it remains unclear." (PMID 41333024, 2025).
cardiovascular disease (2 papers, 2022 to 2025). "We have demonstrated that both pharmacological and genetic approaches to reduce ERO1α activity, which is upregulated in cardiovascular disease, reduces spontaneous SR Ca2+ release and arrhythmic risk without perturbing the fine-tuned redox balance of the SR." (PMID 36425292, 2022).
ERO1A also shares sentences with these, for which no sentence is quoted: cervical cancer (4 papers); lymph node metastasis (3); adenocarcinoma (2); multiple myeloma (2); Oral Squamous Cell Carcinoma (2); preeclampsia (2); brain tumor (1); clear cell renal cell carcinoma (1); endometrial cancer (1); esophageal carcinoma (1); glioblastoma (1); hepatic (1); hepatitis B virus infection (1); Hypothermia (1); liver cirrhosis (1); lung squamous cell carcinoma (1); mastitis (1); muscle disorder (1); myopathy (1); Obesity (1); osteosarcoma (1); prostate carcinoma (1); rectal cancer (1); renal carcinoma (1).